E2F1 (E2F transcription factor 1)
Diseases named in the same sentence as E2F1 in open-access papers (continued):
Sharing a sentence is not in itself a finding about the gene and the disease.
cancer (continued). "Cyclin D1 has prognostic significance through its function in cancer cell proliferation, and also plays an essential role in recruiting transcription factors such as E2F1 and regulates gene transcription via inhibition of p30041,42." (PMID 30054560, 2018). "Expression of Ki-67 and E2F1, which were used as cancer proliferation markers, was investigated by qRT-PCR." (PMID 30054560, 2018). "We also examined the role of HELLS, a chromatin remodeling protein transcriptionally regulated by E2F1 that promotes tumorigenesis in several cancers." (PMID 30220967, 2018). "Recent evidence indicates that E2F1 transcription factor have pivotal roles in the regulation of cellular processes, and is found to be dysregulated in a variety of cancers." (PMID 28569791, 2017). "Accumulating data revealed that E2F1 promote cancer progression by activation transcription of downstream oncogene in both coding and non-coding regions of the genome." (PMID 28569791, 2017). "The most prominent member of this family, E2F1, is involved in a number of essential cancer-related cellular processes such as proliferation, apoptosis, and differentiation." (PMID 28775339, 2017). "Our previous studies have identified several exogenous lectins such as DlFBL, Anguilla japonica lectin 1, as well as Strongylocentrotus purpuratus rhamnose binding lectin interacted with PRMT5 and induced downregulation of E2F1 in cancer cells." (PMID 28335432, 2017). "Among them, E2F1 (E2F transcription factor 1) has drawn much attention because of its complex and diverse functions in different cancers." (PMID 28146423, 2017). "Three pathways demonstrated top priorities, and the one with specific associations with cancers, ‘pathways in cancer,’ was analyzed with its four highlighted genes, namely, BIRC5, E2F1, CCNE1, and CDKN2A, which were validated using Oncomine." (PMID 28316892, 2017). "Altered expression of E2F1 has been reported in many types of human cancer in conjunction with worse patient survival." (PMID 29214011, 2017). "To understand how E2F1 interacts with different molecules and how it mediates cancer-related processes, we constructed a functionally modularized interaction map based on information retrieved from published literature and databases." (PMID 28775339, 2017). "Amplification and/or deregulated expression of the E2F1 gene have been described in several cancer types, including breast, lung and CRC, and high levels of E2F1 are frequently correlated with high-grade tumors or metastases and poor prognosis." (PMID 28704519, 2017). "The comprehensive map of E2F1 regulation and activity is based on manual exploration of over 800 publications related to E2F1 and other E2F family proteins, as well as connected pathways having a role in cancer-related cellular processes." (PMID 28775339, 2017). "Moreover, it has been demonstrated that tight control of E2F1 is crucial for tissue homeostasis and that overexpression of E2F1 may have a causative relationship with cancer development that extends beyond traditional control of the cell cycle, such as invasion and migration." (PMID 28667340, 2017). "With regard to specific 14-3-3 isoforms, there was a report showing that 14-3-3τ up-regulates beclin-1 expression, probably through E2F1, regulating autophagy in cancer cells." (PMID 28404875, 2017).
cancer (continued). "We included additional key players connected to E2F1 directly or through its neighbors along with a post-transcriptional layer of microRNAs in the context of cancer." (PMID 28775339, 2017). "The best-characterized member of the E2F family is the E2F1 transcription factor, which is often amplified in human cancers (cBioPortal for Cancer Genomics)." (PMID 28812991, 2017). "In this study, we also observed a significant upregulation of E2F1 in NSCLC primary carcinoma tissues compared with adjacent carcinoma tissues." (PMID 28667340, 2017). "HPV-related cancers were characterized by mutation of the PIK3CA gene, novel alterations involving loss of TRAF3 function, and amplification of the cell cycle gene E2F1." (PMID 27776338, 2016). "Exogenous E2F1 induced hTERT promoter activity in a number of cancer cells, like sarcoma, gliomas, medulloblastoma, and cervical carcinoma cell lines." (PMID 27367732, 2016). "In this pan-cancer regulatory network, E2F1 acted as a hub with degree 15, indicating that it was involved in many pan-cancer FFLs." (PMID 26655252, 2016). "In human cancer, the pRB-mediated repression of E2F1 is often disrupted through either inactivating the RB1 gene itself, overactivation of cyclinD-CDK4/6 kinases, or inactivation of CDK inhibitors (CKIs)." (PMID 27036039, 2016). "Previous research indicated that mice deficient in E2F1 has more angiogenesis than normal mice and overexpression of E2F1 inhibited the activity of VEGF promoter which induced by hypoxia in cancer cells." (PMID 27708244, 2016). "For example, the TF E2F1, the lncRNA H19 and the miRNA miR-106 had high degrees and were dysregulated in many types of cancer." (PMID 27322142, 2016). "The three MLL2 oncomodules have previously been linked to cancer, with MTOR and E2F1 specifically involved in tumorigenesis in HNSC." (PMID 27095575, 2016). "Cell cycle regulators including E2F1 have previously been shown to regulate metabolism in cancer cells." (PMID 27631473, 2016). "During knock-down of Cdk1 expression, the overactivity of E2F1 increased cell death in cancer cells." (PMID 27385216, 2016). "For example, the lncRNA JPX, the TFs MYC and E2F1 and the miRNA let-7 play crucial roles in human cancers." (PMID 27322142, 2016). "Nonetheless, the location and characteristics of spontaneous carcinomas arising in Rbf/f; K14creERTM;p107−/−and Rbf/f;K14creERTM;E2F1−/− mice are different." (PMID 27708231, 2016). "The effect we now report on E2F1 protein levels indicates a broader impact of this deubiquitylase in cancer through its impact on cell cycle regulation." (PMID 26148512, 2015). "Among these genes, it is worth to notice the presence of important cancer genes such as E2F1, E2F2, and RAD51, which combined starvation and crizotinib down-regulated to a higher extent compared to these treatments alone." (PMID 25909220, 2015). "In the past, the major role reported for E2F1 in cancer progression was its activation of cell cycle progression." (PMID 26356814, 2015). "Although the mechanism of action is poorly understood, it appears that E2f1 activity plays a critical role in the progression of these cancers at an established stage." (PMID 26639898, 2015). "Together, these studies suggest an important role of E2F1 deregulation in cancer as well as the therapeutic potential to harness the apoptotic activity of E2F1 for cancer therapy." (PMID 26039627, 2015). "Our results show that adenovirus E1A induced E2F-1 activity to augment YB-1 expression, which shut down host protein synthesis in cancer cells during adenovirus replication." (PMID 26515462, 2015). "Hyperactivation of the transcriptional factor E2F1 occurs frequently in human cancers and contributes to malignant progression." (PMID 26510456, 2015).
cancer (continued). "Activated AR is a potent stimulator of cell cycle progression from G1 to S phase in cancer cells through the Cyclin D1/retinoblastoma/E2F1 axis." (PMID 25749045, 2015). "The transcription factor E2F1 controls the expression of multiple genes and is frequently overactivated in cancer." (PMID 26510456, 2015). "The E2F site can bind various members of the E2F family, but since E2F1 and RAD51 are often dysregulated in cancer, we focused on the effect of E2F1 on the bidirectional promoter." (PMID 26230935, 2015). "E2f, E2f1, Hif-1 and Isre were the four transcription factors that were found enriched in all cancer types, with E2f1 (p = 0.038) and Hif-1 (p = 0.004) being also enriched in the 72 common upregulated genes." (PMID 26559525, 2015). "All E2F1, Notch pathways, and miRNAs exert the context-dependent, dichotomous, and contradictory roles in cancers." (PMID 26041881, 2015). "Here, the authors show that during cancer progression E2F1 recruits a Pontin/Reptin complex to E2F target genes to open chromatin and increase E2F transcriptional response." (PMID 26639898, 2015). "As predicted, these genetic alterations also differed from HPV-driven cancers involving the base of tongue, which had a higher frequency of activating mutations in PIK3CA, with loss of TRAF3 and amplification of E2F1." (PMID 26395002, 2015). "In those ER-related cancer cells, E2-activated ERα modulates the expression of key cell cycle regulatory genes, including Cyclin D1 and the transcription factor E2F1." (PMID 25221777, 2014). "Activation of nAChRs on cancer cells as a result of tobacco smoke exposure leads to the activation of Src in a β-arrestin-1 dependent manner, leading to the activation of E2F1-mediated transcription of the SCF gene." (PMID 25401222, 2014). "A peptide, isolated from phage clones, based on its binding to an E2F-1 consensus sequence, was cytotoxic against a wide range of cancer cell lines." (PMID 24658650, 2014). "E2F1 is well known for its paradoxical function as oncogene and tumor suppressor in different cancers." (PMID 25373738, 2014). "E2F1 and p73 mRNA and protein expression levels in 100 μg/mL Kuding tea polyphenol treated BcaCD885 cancer cells were higher than those in 25 and 50 μg/mL Kuding tea polyphenol treated cells." (PMID 25100434, 2014). "We considered E2F1 staining as positive when >10% of the cancer cell nuclei showed positive immunostaining, as recommended in a previous study." (PMID 25136922, 2014). "Expression of LMP1 alone in human cancer B-cells was sufficient to efficiently inhibit DOK1 transcription by promoting the formation of a transcriptional repressor complex containing E2F1, pRB, and the DNA methyl-transferase DNMT1." (PMID 24809689, 2014). "E2F1 expression has been found to be upregulated in mutiple cancers, and its overexpression contributes to many tumors development by acting as an important transcript factor regulating key regulator genes that controlling cell proliferation." (PMID 24884417, 2014). "We compared both datasets also for enrichment in four cancer-associated gene expression signatures: up-regulation of HCC-specific oncogenes, or chromosomal instability (CIN) genes, or E2F1 targets, and down-regulation of HCC-specific tumor suppressors." (PMID 25401338, 2014). "We also observed cytotoxicity of NK cells to cancer cells was enhanced by increasing ICAM-1 mediated by E2F1 knockdown." (PMID 24742333, 2014).
cancer (continued). "E2F1 and p73 expressions of Kuding tea polyphenol treated cancer cells were checked by RT-PCR and western blot experiments." (PMID 25100434, 2014). "In human cancer, the pRB-mediated repression of E2F1 is often disrupted through overactivation of cyclinD-CDK4/6 kinases." (PMID 24810364, 2014). "E2F1 is a transcription factor which plays a critical role in cell cycle progression, cell proliferation, apoptosis, and metastasis of cancer cells." (PMID 25373738, 2014). "These miRNAs are not only differentially expressed, but are also adjacent nodes of E2F1 that are frequently involved in the transcription of cancer." (PMID 24137477, 2013). "Being the key mediators of cancer survival, pharmacological inhibition of E2F1 targets is an attractive option for therapeutic intervention against cancer." (PMID 23414419, 2013). "The cyclin–cdk–Rb–E2F1 pathway regulates adipogenesis in addition to its well-described roles in cell cycle regulation and cancer." (PMID 23355973, 2013). "E2F activity is commonly increased in many human cancers, including glioblastoma and lung, ovarian, breast, stomach, and colon cancers, and much evidence supports an oncogenic role for E2F1–3." (PMID 23355973, 2013). "E2F1 was mainly located in the nucleus of cancer cells, whereas in kidney proximal tubule cells cytoplasm and membrane were abundantly immunohistochemically stained." (PMID 24023875, 2013). "Down-regulation of transcription factors E2F1 and DP-1 (product of gene TFDP1) was also linked to cell cycle arrest at G2/M phase in cancer cells." (PMID 24147107, 2013). "As expected, in vitro assay showed that E2F1 overexpression in ccRCC cell line 786-O and A498 boosted cancer cell growth and promoted the cell invasive capacity." (PMID 24023875, 2013). "Numerous studies have reported that E2F1 expression was of clinical significance in different cancers." (PMID 24023875, 2013). "Its oncogenic activity is restricted by the binding of pRB and E2F1 mutants that cannot bind to pRB are potentially responsible for cancer development." (PMID 24154670, 2013). "Topological analysis of the combined networks revealed that many predicted interactions are disrupted in cancer, with E2F1, SP3 and NFκB1 emerging as major regulators." (PMID 22548828, 2012). "In the less differentiated and more aggressive PC-3, we observed the highest levels of E2F1, typical of aggressive cancer phenotype, and of its transcriptional-regulated target cyclin A2." (PMID 22095224, 2012). "Knock-down of E2F1 blocks estrogen regulation of E2F1 target genes, implying that E2F1 is critical for estrogen-regulated proliferation of cancer cells." (PMID 22548828, 2012). "The E2F1 mediated apoptosis pathway is therefore emerging as a promising therapeutic target in controlling cancer development." (PMID 22438805, 2012). "Alterations in the proteins that regulate the early stages of the cell cycle, including Cdk4, D-type cyclins and E2f1, have proven to be important in the development of cancer." (PMID 20090907, 2010). "The RB/E2F pathway is deregulated in many cancers and overexpression of E2F1 also prevents androgen-withdrawal-mediated growth arrest and high levels of E2F1 expression represses neuroendocrine differentiation of androgen independent cells." (PMID 20504375, 2010). "The Rb/p16 pathway is universally disrupted in cancer cells, and, thus, free E2F1 is abundant in cancer cells, allowing replication of Δ24-viruses in most solid tumors." (PMID 21994616, 2010).
cancer (continued). "Collectively, all these data support the conclusion that PUMA is an important mediator of E2F-1-induced cancer cell apoptosis." (PMID 17263886, 2007). "E2F-1-induced cancer cell apoptosis was accompanied by Bax translocation from the cytosol to mitochondria and the induction of caspase-9 activity, suggesting that E2F-1-induced apoptosis is mediated by PUMA through the cytochrome C/Apaf-1-dependent pathway." (PMID 17263886, 2007). "Our previous studies have shown that infection of Ad-E2F-1, an adenovirus vector that expresses the full-length E2F-1 gene, can efficiently induce apoptosis in a wide spectrum of cancer cells in vitro as well as in vivo." (PMID 17263886, 2007). "Our previous studies have shown that adenovirus-mediated overexpression of E2F-1 can efficiently induce apoptosis in a wide spectrum of cancer cell lines." (PMID 17263886, 2007). "The signaling pathways provided here will further enhance insights on the mechanisms of E2F-1-induced cancer cell apoptosis as a strategy for cancer therapy." (PMID 17263886, 2007). "The signaling pathways provided here further enhance our understanding of the mechanisms of E2F-1-induced cancer cell apoptosis, which has the potential for future clinical applications in cancer therapy." (PMID 17263886, 2007). "Together, these results show that ICBP90 expression is altered in cancer cell lines and is upregulated by E2F-1 overexpression with an efficiency depending on the cancer status of the cell line." (PMID 12838312, 2003). "Furthermore, all the cancer cell lines tested exhibited distinct E2F1 activity, whereas normal growing cells, such as WI-38, HUVEC, MEF, and RPE1, did not." (PMID 41511373, 2026). "Although the utilization of distinct E2F1 activity by EREA or ERE73 is expected to be more cancer specific than using promoters of cell cycle-related E2F target genes, there may be some limitations." (PMID 41511373, 2026). "Using the E2F responsive elements of ARF (EREA) and TAp73 (ERE73), we tested whether cancer cell lines possess distinct E2F1 activity." (PMID 41511373, 2026). "Finally, we extended the characterization of distinct E2F1 activity to all of the cancer cell lines available in our laboratory." (PMID 41511373, 2026). "Therefore, in theory, the presence of distinct E2F1 activity is a unique feature of cancer cells enabling their discrimination from normal growing cells." (PMID 41511373, 2026). "E2F1 is hyperactivated in many cancers, promoting rapid proliferation." (PMID 40517236, 2025). "Thus, our results reveal a mechanism by which cancer cells modulate ferroptosis to acquire resistance to immunotherapy and implicate the E2F1-HMGCR axis as a central molecular target for controlling ferroptosis resistance of immune-refractory cancer." (PMID 41339438, 2025). "However, E2f1 overexpression downregulated the expression of genes involved in metabolic pathways, pathways in cancer and infection, and signaling pathways of PI3K-Akt, calcium, and cAMP, among others." (PMID 40761766, 2025). "The inhibition of EGFR was reported to inhibit the activity of E2F1 in cancers." (PMID 41155666, 2025).